IL6 (interleukin 6)
Diseases named in the same sentence as IL6 in open-access papers (continued):
Sharing a sentence is not in itself a finding about the gene and the disease.
Allergy (continued). "Notably, the study established SOCS3 and IL-6 as potential targets for the diagnosis/prognosis of allergy and for the development of reliable therapeutic strategies to control atopic conditions in the near future." (PMID 31251775, 2019). "Moreover, it has been suggested that IL-6 also contributes to allergic disease through IgE production." (PMID 31053741, 2019). "In vivo results were further supported by proliferation and activation of IL6 and IL17A secretion in splenocytes treated with rAni s 1 or rAni s 9, suggesting that IL17 might play a critical role in the Anisakis-associated allergic reaction." (PMID 30245697, 2018). "Th2 cells produce IL-4 and IL-6, which participate in atopic and allergic reactions." (PMID 29383139, 2017). "Dietary intervention with FFBB significantly decreased the HDM allergy-induced increase in IL-6." (PMID 26003185, 2016). "IL-1, IL-6 and TNF-α are the main Th1-type cytokines associated with dry eye syndrome, while the inflammatory Th2-type cytokines IL-4, IL-5 and IFN-γ tend to be increased in allergic diseases." (PMID 26588473, 2015). "The analysis implicated a number of genes with roles in allergy and inflammation, including pro-inflammatory cytokines (IL1A, IL1B, IL6, IL8 and TNF) and factors involved in immune cell activation and recruitment (SELE, SELL, SELP, ICAM1, CSF2, CSF3, CCL2 and CXCL2)." (PMID 21067579, 2010). "More importantly, IL-6 not only functions downstream of IL-17 but also acts as a critical upstream target of IL-17, thus forming a paracrine/autocrine feedback loop that promotes autoimmune and allergic diseases." (PMID 19907660, 2009). "In addition, functional studies have demonstrated that IL6 serum levels and their epigenetic markers might predict allergic disease severity." (PMID 39202464, 2024). "Meanwhile, the present study included a European population and reported that peripheral IL-6 levels may nominally reduce the risk of this allergic disease, which did not consider genetic polymorphisms due to insufficient data." (PMID 37634407, 2023). "However, Bianca found that mice treated with low doses of venom could induce mast cell degranulation and the secretion of MCP-1, IL-6, and IL-1β compared with PBS treated group, suggesting that some patients may be at risk of drug allergy after using “Wugong”." (PMID 35959238, 2022). "IL-6 rs1800796 and rs1800797 polymorphisms were not related to the risk of allergic diseases." (PMID 35368692, 2022). "None of the IL-6 polymorphisms were shared risk variants of allergic diseases." (PMID 35368692, 2022). "So the genetic associations between polymorphisms in IL-6 and allergic diseases risk may be ethnically specific, and maybe we should not try to generalize the combined results of our positive findings to a wider population." (PMID 35368692, 2022). "All of these results indicated that IL-6 polymorphisms might not be the shared risk variants of allergic diseases." (PMID 35368692, 2022). "Moreover, in the study, we investigated the changes in the Th2 cytokine profile–IL-4 (increased production in allergic reactions) and IL-6 (increased production in inflammatory reactions) in order to assess the influence of HBOT on the severity of inflammation in patients with AD." (PMID 33802050, 2021). "Furthermore, IL-6 has not been reported to be a critical player in allergic disease in general although a recent report has linked elevated cardiac IL-6 levels to tree nut induced systemic anaphylaxis for the first time in a mouse model." (PMID 27222655, 2016). "However, we did not measure IL6 in vivo, but the mice during the period of treatment have no obvious abnormal behaviors as anorexia, weight loss, allergy, and so on." (PMID 26444983, 2015). "In allergy-related cytokines, Fat only led to significant increases in multiple BALF cytokines, notably IL-4, IL-5, IL-6, IL-12, IL-13, IL-17, IL-33, TNF-α, and IFN-γ, compared to the normal chow group (NC) (all P < 0.05 or P < 0.01)." (PMID 40998975, 2025).
Allergy (continued). "Macrophages can differentiate into the M1 type, leading to increased secretion of inflammatory factors, such as NO, IL-6, and TNF-α, which ultimately contribute to the progression of allergic diseases." (PMID 39757930, 2025). "Cytokine recruitment, namely, IL-4, IL-5, IL-6, and TNF-α, encourages IgE synthesis in the first phases of an allergic reaction." (PMID 38835658, 2024). "L. acidophilus reduced the serum IL-6 and IL-17 levels and downregulated IL-17A expression, but upregulated CD25, Foxp3, and TGF-β expression in a murine model of allergy." (PMID 35216600, 2022). "Adipose tissue synthesizes and secretes a variety of cytokines and adipokines such as IL-6, TNF, TGF-β, and leptin that drive hypoinflammatory responses and have been proven to contribute to the pathogenesis of allergy." (PMID 35855823, 2022). "IL-6 had been defined as a modulate the adaptive immune response during early T-cell activation and TNF-α, which is a major effector cytokine in allergic reaction and improves mediator expression and cytokine in mast cells." (PMID 35200662, 2022). "The effect of A. cepa supplementation (500 mg twice a day) on 419 cases with respiratory and allergic diseases showed a reduction in TNF-α and IL-6." (PMID 34552650, 2021). "Given this histopathological feature, panels of immunohistochemical markers for TNF-alpha, IL-1, IL-6, IL-17, IL-23, IFN-gamma, and CD-45 were performed, confirming intense areas of inflammatory marker response typical of allergic reaction." (PMID 34576463, 2021). "Platycosides are inhibitors of the production of IL-6, PGD2, LTC4, and β-Hex, therefore presenting potential for allergy symptoms treatment." (PMID 33071794, 2020). "IL-6 had been defined to modulate the adaptive immune response during early T cell activation, and TNF-α, which is a major effector cytokine in allergic reaction, improves mediator expression and cytokines in mast cells." (PMID 33256200, 2020). "The binding of IL-6 to receptor initiates downstream signaling of SOCS3, the auto-inhibitor of IL-6, has been widely studied in allergy." (PMID 31251775, 2019). "In previous allergy models of Anisakis infection in C57BL/6 mice, significantly increased Th17-related cytokines IL6 and IL17A were observed after subchronic treatment (7 times over 15 days) with recombinant Ani s 1 (rAni s 1) allergen." (PMID 30245697, 2018). "The markers of inflammation and allergic reaction, IFN-γ, TNF-α, IL-4, and IL-6, were suppressed, especially after treatment with 100 μg/mL ST." (PMID 29849717, 2018). "Hence, analysis of allergen-naive samples identified multiple epigenetic changes induced by maternal allergy but these were not linked to major background transcription alterations on their own (with the exception of a minor transcriptional shift in the IL-6 signaling pathway)." (PMID 23950928, 2013). "Increased ratio of proinflammatory cytokines (IL-17, TSLP, and IL-6) versus regulatory cytokines (IL-10 and TGF-β) in severe allergic diseases would activate further the balance shift and form a positive feedback loop in chronic inflammation." (PMID 23283296, 2008). "Increasing evidence implicates IL6 in promoting the development of TH2 mediated diseases, like allergies." (PMID 16759385, 2006). "We did not test the effect of IL-6 inhibitors in our study due to the previous patient’s history of severe allergic reaction/adverse effect to anti-IL-6 receptor antibody treatment." (PMID 41168503, 2025). "In contrast to these findings, we observed no elevated IL-6 levels prior to surgery within the allergy group." (PMID 38098024, 2023). "Our results showed that HPE could inhibit the production of IL-4, IL-6, IL-13 and TNF-α released by mast cells, thus, ultimately, compromised mast cell-mediated allergic diseases." (PMID 38012745, 2023). "However, no eye rubbing or scratching was observed during the period of allergy induction in our study, while elevated TNF-α, IL-1β, and IL-6 mRNA levels were still confirmed." (PMID 35692541, 2022).
Allergy (continued). "This study provides a possibility that the improvement effect of SD treatment on allergies and inflammation in AR mice may be related to the TLR4/TRAF6/NF-κB and IL-6/ROR-γt/STAT3 pathways and intestinal microflora modulation." (PMID 36276863, 2022). "In infants without allergies, the phase pair abundance of Ruminococcaceae was negatively correlated with IL-6 and TNF-α induced by Toll-like receptor-2 (TLR-2), and the lower relative abundance of Ruminococcaceae appeared to be related to food sensitization." (PMID 35911834, 2022). "An important issue that needs to be emphasized considering in vitro tests is the fact that cytokines are determined in various conditions and various diseases; however, only certain cytokines (i.e., TNF-α, IL-2, IL-4, IL-5, IL-6, IL-10, IL-13, and IFN-γ) are important in allergic reactions." (PMID 36590449, 2022). "Furthermore, the polymorphic study of IL-6 promoter region (IL-6 174-G/C) in atopic population has reasserted the importance of SOCS3 and IL-6 in the diagnosis and prognosis of allergy." (PMID 31251775, 2019). "While the expression of TNF-α, IL-6, GFAP, and SP, together with microglial activation, follows the pattern of a Th2 cell-dependent allergic reaction, the exact mechanism of their increase or function in the hippocampus is unknown at this time." (PMID 29849816, 2018). "LTC4, IL-6, IL-1, MCP-1/CCL2, and TNF-α play important roles in the development of allergic diseases, and their release and synthesis could be increased in various allergic diseases." (PMID 27200102, 2016). "Budesonide, but not 1% GOS, normalized HDM allergy-induced increase of IL-6 concentrations to the control level." (PMID 25849971, 2015). "In this study, cytokine secretion of IL-6 is lower after Ppg stimulation in CBMC of mothers with as compared to mothers without allergy." (PMID 16551363, 2006). "A binary classification of TGF-β activity as either high (in the presence of IL-1β and IL-6) or low (in the presence or absence of IL-1β and IL-6) is proposed to differentiate between allergy patients prone to cancer and metabolic dysregulations and those less prone." (PMID 38629073, 2024). "Ethnicity was significantly associated with IL-6 sRA (p = 0.02517006) and ILT-2 (p = 0.01750944) protein counts, whereas participants reporting allergies showed significantly lower IgD (p = 0.01235089) protein counts compared to those reporting no allergy." (PMID 39700097, 2024). "Basolateral challenge of the epithelium with HIS induced upregulation of pro-inflammatory cytokines as IL-6 and IL-8; however, other major cytokines involved in the allergic reaction (IL-25, IL-33, and TSLP) were not detectable in the epithelium with or without the addition of HIS." (PMID 38933682, 2024). "Interestingly within the allergy group and similar non-allergy patients (matched pairs) IL-6 was not detectable prior to surgery." (PMID 38098024, 2023). "The production of interleukin (IL)-1, IL-6, IL-12, interferon (IFN)-γ, and tumor necrosis factor (TNF)-α promotes Th1 differentiation; IL-17A, IL-17F, IL-21, IL-22, and IFN-γ promote Th17 differentiation; IL-4, IL-5, IL-13, IL-9, and IL-6 promote Th2 differentiation involved in allergic reactions." (PMID 37372929, 2023). "Even in non-Th2 allergies, IL-17 induces airway epithelial cells to produce chemokines CXCL1 and CXCL8 to promote neutrophil recruitment while stimulating fibroblasts and macrophages to secrete cytokines such as GM-CSF, TNF, IL-1, IL-8, and IL-6 to enhance inflammatory responses." (PMID 35855823, 2022). "Basophils have pre-formed secretory granules containing pro-inflammatory cytokines, such as IL4, IL6, IL13, TSLP, GM-CSF and VEGF, and chemokines, such as CCL3, CCL4, CCL5 and CXCL8/IL8, in addition to histamine and granzyme B, and are widely known as a key player in allergy and parasitic infection." (PMID 36211375, 2022).
Allergy (continued). "Interestingly, a reduced release of IL-6 was observed in CB-derived monocytes after stimulation with LPS in neonates with maternal allergy compared to non-allergic controls." (PMID 31711888, 2020). "YPFS has a certain effect on Th2-type cytokines such as (IL-4, IL-6, IL-10, and IL-17) and Th1 type cytokines such as (IFN-γ and tumor necrosis factor-α), and YPFS mainly exerts pharmacological effects such as immune regulation and anti-allergy and anti-inflammatory by acting on these cytokines." (PMID 31885639, 2019). "There might be a concern of cow’s milk and hen’s egg allergy regarding the increase in IL-6 levels, but none of our stunted study children showed or reported any sign of food allergy throughout the intervention period." (PMID 31394828, 2019). "Based on this observation, we suggest that the inhibition of IL‐6 classic signalling per se, although potentially beneficial to attenuate local allergic immune responses, on balance is unlikely to be a successful therapeutic approach for allergic diseases." (PMID 31223480, 2019). "Mast cells may also be able to selectively release proinflammatory mediators without the degranulation typical of allergic reactions; for example, IL-1 may induce the selective release of IL-6." (PMID 29849717, 2018). "We found that IL-6 and IL-6R existed in cells around the inflammatory tissues of RA patients, inferring that IL-6 was correlated with ARD joints, and played an essential role in its pathogenesis, the effect of which is evident in allergic reaction-related parts." (PMID 25097512, 2014). "In addition, IL-10 can inhibit activated monocytes from secreting interleukin-1 (IL-1) and interleukin-6 (IL-6), suppress the release of TNF-α by macrophages, and inhibit the activation of mast cells and the secretion of their cytokines, thereby participating in the regulation of allergic reactions." (PMID 40264774, 2025). "Fifth, the influence of IL-4 combined with other genes (such as IL-6, IL-10, IL-17, IL-27, IFN-γ, etc.)or the environments on allergies has not been analyzed." (PMID 33834211, 2021). "Interestingly, IL-6 was more highly expressed in nasal polyps in allergic individuals than in nasal polyps in non-allergic individuals, suggesting that IL-6 and the IL-6 signaling pathway could play a potential role in CRSwNP in patients with inhalation allergies." (PMID 29564208, 2018). "The TLR4 priming significantly increase expression of IL-6, IL-8, GM-CSF, IP-10, and RANTES in hTMSCs irrespective of allergy state, while the TLR3 priming did not significantly affect the secretion of these cytokines." (PMID 26376485, 2015). "In this study, hTMSCs secreted high amounts of IL-6 and IL-8, but not IL-10, TNF-α, or IFN-γ, irrespective of allergy state." (PMID 26376485, 2015). "The parameters for inflammatory diseases (CRP, TNFα and IL-6) and allergic diseases (IgE and eosinophil) were similarly unchanged, suggesting that ARA intake does not evoke inflammatory or allergic diseases." (PMID 22188761, 2011).
cervical carcinoma (170 papers, 2002 to 2026). A carcinoma arising from either the exocervical squamous epithelium or the endocervical glandular epithelium. "In summary, our pooled data indicated that the XRCC3 RS861539, TNF-α rs1800629, and IL-6 rs1800795 genetic variants were associated with susceptibility to cervical cancer globally." (PMID 34837895, 2021). "Allele G of IL-6 rs1800795 was less frequent in cervical cancer group compared with controls (70.8% vs. 92.9%, p < 0.001)." (PMID 34684062, 2021). "Allele G and genotype GG of IL-6 rs1800795 were associated with a lower risk of cervical cancer, but allele C and genotype CC were associated with a higher cervical cancer risk in the Lithuanian population." (PMID 34684062, 2021). "Gupta and colleagues found that the presence of −597 G allele of IL-6-597A/G increases the risk of cervical cancer in the study population by up to 6.2 times (p < 0.001)." (PMID 34684062, 2021). "Allele C of IL-6 rs1800795 and genotype CC of IL-6 rs1800795 were more frequent among women with cervical cancer than in controls (74.2% vs. 56%, p < 0.012 and 29.2% vs. 7.1%, p < 0.001 respectively)." (PMID 34684062, 2021). "They reported that the IL-6 -174G>C polymorphism was a low-penetrance susceptibility variant for cervical cancer." (PMID 34582655, 2021). "The major finding of our study is the significant association of C allele and CC genotype of IL-6 1800795 gene with cervical cancer in the Lithuanian population." (PMID 34684062, 2021). "Different results compared to our data were observed in Shi’s study, where IL-6 rs1800797 polymorphism confers a higher risk of cervical cancer in the Chinese population." (PMID 34684062, 2021). "Allele C of IL-6 rs1800795 was associated with a higher risk of cervical cancer by 2.26-fold and genotype CC by 5.37-fold." (PMID 34684062, 2021). "The major finding of the study is the significant association of C allele and CC genotype of IL-6 1800795 gene with cervical cancer in the Lithuanian population." (PMID 34684062, 2021). "Pooled data from all eligible studies showed that the IL-6 rs1800795 polymorphism was significantly associated with cervical cancer risk in overall population and among Asian women." (PMID 34837895, 2021). "Our study results demonstrated an increased OR for C allele and CC genotype of IL-6 rs 1800795 gene in cervical cancer cases compared to controls." (PMID 34684062, 2021). "There was a significant association between XRCC3 RS861539, TNF-α rs1800629, and IL-6 rs1800795 polymorphisms and an increased risk of cervical carcinoma in overall population." (PMID 34837895, 2021). "Investigating the association of cervical levels of IL-6 and IL-8 with the treatment response rate as well as the survival rate of patients with cervical cancer, should also be done in future studies." (PMID 33906316, 2021). "IL-6 cytokines have also been implicated in the progression and metastasis of breast, prostate, lung, and cervical cancer, highlighting the importance of these cytokines in the tumor–bone microenvironment." (PMID 32023849, 2020). "Activation of IL-6/STAT3 signalling was observed in mice implanted with cervical cancer cells containing high-risk HPV E6." (PMID 33076322, 2020). "Up to now, many related articles have evaluated the association of IL-12 rs3212227 and IL-6 rs1800795 polymorphisms with risk of cervical cancer." (PMID 32458622, 2020). "Some epidemiological studies suggested that IL-12B rs3212227 and IL-6 rs1800795 polymorphisms are associated with an increased risk of cervical cancer." (PMID 32458622, 2020). "Stratified analysis by ethnicity revealed that both IL-12B rs3212227 and IL-6 rs1800795 polymorphisms were associated with risk of cervical cancer in Asian women." (PMID 32458622, 2020). "Primary studies have shown that the IL-12B rs3212227 and IL-6 rs1800795 polymorphisms are associated with an increased risk of cervical cancer." (PMID 32458622, 2020).